NANOG (Nanog homeobox)
Diseases named in the same sentence as NANOG in open-access papers (continued):
Sharing a sentence is not in itself a finding about the gene and the disease.
cancer (continued). "In addition, western blotting revealed that overexpression of MPC1 decreased the level of cancer stem cell (CSC) markers, including NANOG, OCT4, and SOX2 in LAC cells, while knockdown of MPC1 increased the level of these markers." (PMID 30770798, 2019). "Both GLIS1 and NANOG have been indicated to activate certain components of the WNT pathway in reprogramming, and WNT and LIN28 co-amplify the expression of their target genes in cancer cells." (PMID 31806618, 2019). "Further results from immunoblot suggest that CHTOP knockdown not only decreased the protein expressions of two representative surface markers of cancer stem cell (CD44 and ALDH1) but also inhibited the protein expressions of two important transcriptional makers of cancer stem cell (SOX-2 and NANOG)." (PMID 30910850, 2019). "Cancer cells isolated by the sphere formation assay displayed self‐renewal properties, upregulation of EMT markers (vimentin, Snail/Slug and N‐cadherin), stemness and developmental genes (CD105, CD133, CXCR4, NANOG, MYCN, and WNT)." (PMID 30883740, 2019). "NANOG promotes multidrug resistance and immune evasion by increasing HDAC1; consequently, the inhibition of HDAC improves antigen-specific adoptive T-cell therapy as well as anti-cancer drug sensitivity." (PMID 31151327, 2019). "NANOG (NANOG1) has 11 pseudogenes and at least NANOGP4, P5 and P8 are expressed in cancer cells." (PMID 30846719, 2019). "The results in the present study exhibited that QYHJ has a significant inhibitory effect in the mRNA expression of NANOG, which implied that the inhibition effect of QYHJ may be related with the cancer stem cell." (PMID 31147453, 2019). "Furthermore, the six pluripotency genes examined, including OSKM, NANOG and REX1, are already expressed in the parental CRC cells, as reported for other cancer cells." (PMID 30025541, 2018). "OCT4, SOX2, NANOG, Krüppel-like factor 4 (KLF4) and c-MYC play a significant role in triggering pluripotency in somatic cells, and they have been used to identify CSC subpopulations within various types of cancer." (PMID 30177970, 2018). "Using the same cut-off as of training cohort, the individual sensitivity and specificity for cancer detection were 35.0% (21/60) and 91.3% (167/183) for CD24, 35.0% (21/60) and 83.6% (153/183) for CD49f, and 51.7% (31/60) and 88.5% (162/183) for NANOG, respectively." (PMID 30327565, 2018). "Moreover, FOXC1 knockdown decreased expression of Oct4, NANOG, SOX2 and ABCG2, which are important downstream target genes of beta-catenin in regulating cancer stemness." (PMID 30189871, 2018). "Furthermore, we verified that cyclin D1 affects EMT in OCSLCs, whereas in other studies, NANOG and c-MYC were reported to be involved in OCSC regulation and acted as cancer stem related-markers." (PMID 30518424, 2018). "Western blot assay showed that silence of PCAT3 or PCAT9 decreased the protein levels of OCT4, SOX2, NANOG and VEGF in LNCaP and 22Rv1 cells, suggesting that PCAT3 and PCAT9 may modulate the properties of angiogenesis and cancer stem cells in PCa." (PMID 29552304, 2018). "Tumor growth and progression is driven by cancer stem cells that possess self-renewal ability, and the maintenance of CSCs is regulated by key embryonic stem cell transcription factors (i.e. SOX2, OCT4 and NANOG)." (PMID 28068409, 2017). "Experimental results showed that culturing cancer cells on chitosan increased cell motility, drug resistance, quiescent population, self-renewal capacity, and the expression levels of stemness and CSC marker genes, such as OCT4, NANOG, CD133, CD44, and EpCAM." (PMID 28367998, 2017). "Since our molecular analyses indicated an activation of stemness in the SL region, we next assessed the gene expression levels of specific HCC/differentiation markers (AFP, GPC3, albumin) as well as the selected (cancer-) stemness markers (EpCAM, CD133, CK19) and pluripotency genes (NANOG)." (PMID 28415775, 2017).
cancer (continued). "We observed that cancer cells efficiently internalized hESCs-Exo, and that these exosomes contained both mRNA and proteins of specific hESCs pluripotency markers (i.e. SOX2, OCT4, NANOG, SSEA4)." (PMID 28068409, 2017). "Inhibiting the NANOG pathway may potentially decrease the CSC phenotype in CRC cells and sensitize cancer cells to chemotherapy." (PMID 28453235, 2017). "Moreover, NANOG was reported to be upregulated by a number of factors such as STAT3, Hedgehog signaling, hypoxia, etc., in human cancers, and repression or ablation of NANOG inhibited tumor initiation." (PMID 28116670, 2017). "Many stem-like cells commonly overexpress markers such as NANOG, OCT-4, SOX-2, KLF-4 and C-MYC, where these genes play important roles in the regulation of self-renewal and tumorigenicity in CSC populations of several cancer types." (PMID 29069808, 2017). "Several studies have shown that the expression level of NANOG is high in in a variety of cancers, including those of the prostate, and low or absent in normal tissues." (PMID 29156833, 2017). "Strong expression of NANOG or MK was significantly correlated with histologically high-grade OSCCs (p < 0.001), whereas weak or negative expression of NANOG (p < 0.05) or MK (p < 0.001) predominantly occurred in well-differentiated carcinomas." (PMID 29113102, 2017). "We and others have reported the expression of embryonic proteins, including carcino-embryonic-antigen (CEA), alkaline-phosphatase, and NANOG, in CRC and other cancers, which may contain undifferentiated multipotent cancer cells." (PMID 27207017, 2016). "BORIS-positive cells expressed cancer stem genes including CD44, ALDH1, NANOG, OCT4 and SOX2." (PMID 26849232, 2016). "YAP-TEAD signaling was previously shown to activate the promoters of OCT-3/4 and NANOG stem cell markers, and recent results showed overexpression of CD90, a cancer stem cell marker, in HCC cell lines in which YAP1 expression was stimulated as a consequence of TAZ inhibition." (PMID 27359056, 2016). "In addition to cell surface markers, several pathways and molecules that control self-renewal and differentiation of cancer stem cells and normal stem cells have been identified including p-STAT3, NOTCH, C-Myc, NANOG, OCT4, SOX2 and others." (PMID 27472461, 2016). "YY1 shares many properties with cancer stem cells (CSCs) that drive tumorigenesis, metastasis and drug resistance and are regulated by overexpression of certain transcription factors, including SOX2, OCT4 (POU5F1), BMI1 and NANOG." (PMID 27225481, 2016). "Interestingly, the GBM cell lines U87MG and U251 were found to express cancer stem cell markers CD133, NANOG, Oct4 and Sox2." (PMID 26983719, 2016). "However, another study released alongside showed that depletion of ATOH8 reprogramed non-cancer stem cells into cancer stem cells by directly releasing AFP, CD133, OCT4 and NANOG." (PMID 27049918, 2016). "Importantly, BORIS-silencing led to down-regulation of hTERT, stem cell (NANOG, OCT4, SOX2 and BMI1) and cancer stem cell markers (ABCG2, CD44 and ALDH1) genes." (PMID 26185996, 2015). "Moreover, the 3D growth microenvironment induced the cancer cells to express the reprogramming transcription factors OCT4, SOX2, NANOG and LIN28." (PMID 25883172, 2015). "Cancer stem cells are molecularly characterized based on the expression of various cell surface receptors including integrin a6 (CD49f), integrin b1 (CD29), hyaluronan receptor (CD44), and the stem cell self-renewal transcription factors NANOG, OCT4, and SOX2." (PMID 26005638, 2015). "Strong expression of NANOG was significantly correlated with histologically high-grade OSCCs (p < 0.001), whereas weak or negative expression of NANOG predominantly occurred in well-differentiated carcinomas (p = 0.018)." (PMID 26626427, 2015).
cancer (continued). "NANOG and LIN28, which are induced pluripotent stem cell-related genes and master transcription factors essential for maintaining stem cell phenotypes, and high ALDH activity have been found in stem cell populations in various types of cancers." (PMID 25260650, 2014). "In this study, a large number of strongly positive NANOG and/or OCT4 cancer cells were observed." (PMID 25120646, 2014). "In this study, the NANOG protein was detected in the nucleus of cancer cells, but was not expressed in hyperplastic glandular cells." (PMID 25120646, 2014). "Furthermore, the expression of representative cancer stem cell genes and related proteins, including SOX2, Oct4, and NANOG, was upregulated in spheres compared with those detected in parental cells, at both the RNA and protein levels." (PMID 22359637, 2012). "Some variants between the reference sequences of NANOG and NANOGP8 utilized in cancer research to distinguish RT-PCR products are polymorphic within NANOG or NANOGP8 and thus are not universally reliable as distinguishing features." (PMID 23173096, 2012). "The expression of OCT4, NANOG, NESTIN, and BRY was tested in cancer cell lines also." (PMID 21785609, 2011). "Moreover, in silico results showed that meranzin hydrate may downregulate the protein expression of two cancer stemness markers, ALDH1A1 and NANOG, which was further validated by in vitro Western blot analysis." (PMID 41473403, 2026). "Similarly, in a study of head and neck cancer, cancer cells expressed high levels of NANOG, OCT4, SOX2 and EpCAM when ARID1A was absent." (PMID 40429787, 2025). "In the same way, a combination of NANOG and OCT4 may be a predictor for cancer recurrence." (PMID 40804837, 2025). "Stemness-related genes have been found, such as SOX2 (sex-determining region Y-box 2), NANOG (Nanog homeobox), and OCT4 (octamer-binding protein 4), along with the expression of the surface markers CD133+ and CD44+ and chemokine markers such as CXCR4 on cancer stem cells as stemness markers." (PMID 39684461, 2024). "Consistent with the genomic results, we found that GluOC promoted the protein expression of OCT4, NANOG, and SOX2, while Y-27632 attenuated this effect, but the addition of GluOC significantly alleviated the effect of the inhibitor and induced the proliferation of cancer cells." (PMID 39054484, 2024). "Moreover, cancer cells transduced with shRNA against NANOG failed to form visible or microscopic hepatic liver colonies, compared with parental cells in a mouse model of CRC." (PMID 39273409, 2024). "The expression of PD-L1 on cancer cells can be directly upregulated by MACC1 itself, or through secondary factors such as HGF/c-MET, via activated STAT1/3, PI3K/Akt, or Wnt/β-catenin signaling, from metabolic alterations or by promoting cellular stemness via Oct4/NANOG/LGR5." (PMID 39580452, 2024). "Conversely, pluripotency transcription factors, including NANOG, POU5F1 (encoding OCT4), and TFCP2L1 (encoding LBP9), that control HERVH activity in human ES cells associated with HERVH-CALB1 expression in other cancer types, but not in LUSC." (PMID 37192000, 2023). "Since cancer stem cells (CSCs) have the ability to self-renew and are less sensitive to therapy which makes them often responsible for resistance occurrence, we checked the gene expression levels of stemness-related transcription factors, OCT4, NANOG, and SOX2." (PMID 37239024, 2023). "The self-renewal characteristic of cancer cells can be attributed to the phenotypes of stem cells, characterized by increased expression levels of stemness transcription factors such as OCT4 (octamer-binding transcription factor 4), NANOG (Nanog homeobox), and SOX2 (sex-determining region Y-box 2)." (PMID 38132948, 2023).
cancer (continued). "With regards to human cancer cell lines, that is brain, uterine cervix, lung, colon, bladder, and synovium derived cell lines, double-network hydrogel has been utilized to create spheroids with elevated levels of stemness-related genes SOX2, OCT3/4, and NANOG in vitro within 24h of seeding." (PMID 37614497, 2023). "We have previously reported that embryonic stemness genes, specifically NANOG and OCT4, which are members of the DNA-binding homeobox transcription factor family, exhibit a higher expression in CSCs compared to normal neural stem cells and other cancer cells in GBM." (PMID 37372456, 2023). "Several important signaling pathways, including JAK & STAT, WNT and β-catenin, NANOG and NOTCH modulate the cancer stemness, which can be gained during dedifferentiation and may promote tumor aggressiveness including the potential for tumor metastasis and regeneration." (PMID 36830680, 2023). "The significance of the NANOG‐pERK reciprocal regulatory loop in establishing heterogeneity and ERK signaling dynamics may not be limited to pluripotent cells but could be relevant in cancer stem cells and tumor heterogeneity." (PMID 36066347, 2022). "Importantly, the growth-enhancing effects of IL-6 on cancer cells also extend to cancer stem cells, capable of self-renewal and expansion, which require STAT3 to act synergistically with stem cell transcription factors such as NANOG." (PMID 36313280, 2022). "In addition, an increased expression of NANOG ⇒ STAT3 ⇒ miR21 was followed by the down-regulation of programmed cell death 4 (PDCD4), resulting in the enhanced anti-apoptotic and chemoresistance properties of cancer cells." (PMID 36497144, 2022). "However, its role in association with pAMPKα, and its clinical significance in EOC have not been elucidated even though AMPK is known to degrade NANOG in various human cancers." (PMID 36114703, 2022). "In addition, knockdown of CMTM2 could antagonize the effects of SJZ on SGC7901 cells' expression of SOX2, NANOG, and CD44 and their cancer stem cell-like properties." (PMID 35873650, 2022). "There are almost no research reports about why NANOG signaling differs depending on cancer types." (PMID 36497144, 2022). "Along with the positive immunofluorescence for cancer stem cell biomarkers (OCT4, NANOG, and SOX-2), these findings indicated the involvement of primitive embryonic cells as the origin of MCMT and concluded that MCMT may not come from colliding tumors, but from a single stem cell." (PMID 36187098, 2022). "Together with NANOG, SOX2, and other transcription regulators, Oct4 activated both protein-coding genes and non-coding RNAs necessary for pluripotency which correlated with cell fate determination, proliferation, metastasis, drug resistance and invaded from apoptosis in cancer cells." (PMID 34613998, 2021). "g., transfection) of stemness genes, such as OCT3, SOX2, KLF4, MYC, NOTCH1, NANOG, and LIN28, as well as epithelial-mesenchymal transition (EMT) genes (ZEB1, SNAI, VIM, TWIST, etc.), leads to stem phenotype induction and increased stem-like cancer cell activity." (PMID 32523653, 2020). "As it has been shown that NANOG and PRC2 co-occupy many PRC2 targets in human ES cells, our data suggested the possibility that NANEP5 might interact with PRC2 components to regulate target genes in cancer cells." (PMID 30846719, 2019). "Next, to investigate the role of CD133 in cancer stemness we examined acquisition of CSC‐like properties, such as an increased ability to form tumor spheres, increased ALDH activity, and increased expression of stem cell‐like markers such as ALDHA1, OCT4, and NANOG." (PMID 31372592, 2019). "To date, attempts have been made to target stemness markers, such as STAT3 and NANOG, as well as pathways that regulate malignant stemness, most notably the Wnt/β-catenin, Notch, hedgehog, and JAK-STAT pathways, which promote stemness features in various cancers." (PMID 31137841, 2019).
cancer (continued). "Because NANOG expression is increased in cancer stem cells and research has suggested that NANOGP8 may be involved in the reprogramming of normal cells to cancer cells, the identification of exosomal NANOG DNA fragments provides further insight on the mechanisms of cancer formation and metastasis." (PMID 29787607, 2018). "However, to the best of our knowledge, the correlation between NANOG and MK expression in cancer specimens has not been studied." (PMID 29113102, 2017). "Moreover, the cancer stem cell markers EPCAM and NANOG were up-regulated by HOXB7." (PMID 28646927, 2017). "In this study, we analysed eleven death-from-cancer signatures in survival of cancer patients and demonstrated that USP22 plays vital roles in gastric CSC self-renewal and GC progression by stabilizing BMI1 and regulating the expression of stemness genes such as CD133, SOX2, OCT4 and NANOG." (PMID 28415621, 2017). "Furthermore, cancer stem cell markers, such as CD133, SOX2, OCT4 and NANOG were down-regulated." (PMID 28415621, 2017). "Of note, CD117 showed a promoting effect on cell proliferation similar to that of the cancer stem cell markers OCT4 and NANOG, which also suggested that CD117 might function as a cancer stem marker in OS; however, CD117 showed a negative regulation of OS drug resistance in this study." (PMID 27056900, 2016). "Cancer cell proliferation and capacity for transformation were impaired in the CD133 stable knockdown cell lines, which were accompanied by the suppression of stemness genes including NANOG, OCT4, SOX2, and c-MYC, suggesting that CD133 expression is required for tumor tissue growth and survival." (PMID 26539911, 2015). "Interestingly, mRNAs of OCT4 and NANOG were detected by RT-PCR in all cancer lines while the proteins were not revealed by immunostaining." (PMID 21785609, 2011). "Unlike the NCCIT cells, expression of OCT4, SOX2 and NANOG could not be detected in any primary cancer cell line tested." (PMID 18847459, 2008). "Given that cancer progression involves the loss of differentiation and acquisition of stem cell-like features, we examined the effect of TC2N expression on three stem cell markers (SOX2, OCT4, and NANOG) in normal lung (without urethane treatment) and urethane-induced lung tumor tissues." (PMID 39849581, 2025). "Furthermore, NANOG may be clinically relevant in monitoring patients treated with a CSC inhibitor, such as Napabucasin (BBI608), whose strong anti-CSC effect has already been demonstrated in vitro and in vivo in a broad range of cancer types." (PMID 34834576, 2021). "Furthermore, levels of NANOG and HSP90A within the tumor correlated strongly with disease progression and survival in cancer patients, indicating that the expression status of HSP90A (either alone or in conjunction with NANOG) within tumor tissue may serve as an excellent prognostic marker." (PMID 31992715, 2020). "To further investigate whether cancer cells cultured in a 3D matrigel microenvironment acquire stem cell–like characteristics when compared with 2D monolayer cells, we measured the expressions of the stem cell markers OCT4, SOX2, NANOG, c-MYC and LIN28 in both 2D- and 3D-cultured A549 cells." (PMID 25883172, 2015). "However, it is not clear whether NANOG or its pseudogenes contribute to the malignant potential of cancer." (PMID 26087476, 2015). "RT-PCR analysis showed significantly (p<0.01) higher expression of prominent stem cell factors—SOX2, OCT4, and NANOG—in CD133+EpCAM+ cells compared to their negative fractions, corroborating their characterization as cancer stem-like cells." (PMID 40677705, 2025). "Re-expression of NANOG occurs in GCNIS, SEM and EC, but not in differentiated TGCTs, suggesting that reacquisition of pluripotency is a key feature of malignant tumours." (PMID 38693576, 2024).